TRAF4 (TNF receptor associated factor 4)
Diseases named in the same sentence as TRAF4 in open-access papers (continued):
Sharing a sentence is not in itself a finding about the gene and the disease.
glioblastoma (8 papers, 2022 to 2025). The most malignant astrocytic tumor (WHO grade IV). "In conclusion, our results suggest that loss of TRAF4 significantly inhibits glioblastoma proliferation." (PMID 36077559, 2022). "The pharmacological inhibition of TRAF4 by risperidone has been demonstrated to be an effective means of inhibiting tumor self-renewal in glioblastoma, with a concomitant reversal of temozolomide (TMZ) resistance." (PMID 40990020, 2025). "In this context, risperidone acts as a pharmacological inhibitor of TRAF4, effectively suppressing the self-renewal of glioblastoma (GBM), eradicating tumor pathogenicity, and reversing resistance to temozolomide." (PMID 38521878, 2024). "Recently study showed that TRAF4-mediated atypical ubiquitination of SET domain bifurcated 1 induced the activation of the AKT pathway to facilitate glioblastoma proliferation." (PMID 38164179, 2024). "The results of MTT experiments showed that knockdown of TRAF4 significantly inhibited the cell proliferation of glioblastoma cells." (PMID 36077559, 2022). "Restoring SETDB1 expression in TRAF4 knockdown glioblastoma cells partially restored cell growth and proliferation." (PMID 36077559, 2022). "To further confirm that TRAF4 promoted glioblastoma proliferation through regulating the stability and function of SETDB1, we overexpressed SETDB1 in TRAF4 knockdown glioblastoma cells." (PMID 36077559, 2022). "To verify the role of TRAF4 in glioblastoma cells, we knocked down the expression of TRAF4 in U87-MG and LN-229 cells using shRNA lentiviral constructs." (PMID 36077559, 2022). "Clinical data from tumor patients show that TRAF4 is significantly overexpressed in glioblastoma; however, there is little research on the role and regulatory mechanism of TRAF4 in glioblastoma proliferation." (PMID 36077559, 2022). "The colony formation assays suggested that overexpression of SETDB1 in TRAF4-knockdown glioblastoma partially restored cell growth." (PMID 36077559, 2022). "In previous experiments, we found that knockdown of TRAF4 inhibited the proliferation of glioblastoma." (PMID 36077559, 2022). "What role does TRAF4 play in the pathogenesis of glioblastoma, and which signaling pathways are involved?" (PMID 36077559, 2022). "Taken together, our experimental results suggested that overexpression of SETDB1 can restore the proliferation of TRAF4 knockdown glioblastoma cells to a certain extent." (PMID 36077559, 2022). "Increased expression levels of DLEU1 and TRAF4 in glioblastoma multiforme (GBM) tissues promote GBM cell proliferation and regulate cell migration through the Hippo signaling pathway and Wnt signaling pathway." (PMID 35242717, 2022). "Knockdown of TRAF4 significantly inhibited the growth, proliferation, migration, and invasion of glioblastoma cells." (PMID 36077559, 2022). "EdU incorporation experiments also indicated that the proliferative capacity of TRAF4-knockdown glioblastoma cells was significantly increased following SETDB1 overexpression." (PMID 36077559, 2022). "Further immunoprecipitation experiments in glioblastoma cells showed that endogenous TRAF4 likewise interacted with SETDB1." (PMID 36077559, 2022). "The results showed that the tumor formation of glioblastoma was significantly inhibited following TRAF4 knockdown." (PMID 36077559, 2022). "Moving further than previous study, our study characterized TRAF4 in glioblastoma systematically and explored the effect of TRAF4 on the clone formation, self-renewal, and in vivo tumorigenesis of glioblastoma cells." (PMID 36077559, 2022). "Transwell assays were employed to detect cell migration and invasion, and the results showed that knockdown of TRAF4 significantly inhibited the migration and invasion of glioblastoma cells." (PMID 36077559, 2022). "5-ethynyl-2′-deoxyuridine (EdU) incorporation experiments showed that knockdown of TRAF4 reduced DNA synthesis ability and proliferation in glioblastoma cells." (PMID 36077559, 2022).
glioblastoma (continued). "Overall, the results of analyzing the database suggested that TRAF4 is involved in the proliferation of glioblastoma, consistent with the findings in our cellular experiments." (PMID 36077559, 2022). "Our research elucidates a novel mechanism showing how TRAF4 is involved in glioblastoma proliferation and furthers our understanding of the role of TRAF4 ubiquitination." (PMID 36077559, 2022). "The results show that across multiple cancers, TRAF4 was more highly expressed in most tumors than that in the corresponding paracancerous tissues, including glioblastoma." (PMID 36077559, 2022). "Here, we report that TRAF4 is significantly overexpressed in glioblastoma and is important for cell growth, proliferation, migration, and invasion." (PMID 36077559, 2022). "The results of Western blotting showed that knockdown of TRAF4 inhibited the activation of AKT pathway in glioblastoma cells." (PMID 36077559, 2022). "In our findings, the effect of TRAF4 on the malignant phenotype of glioblastoma cells is consistent with previous findings." (PMID 36077559, 2022). "We found that activation of the AKT pathway is inhibited following TRAF4 knockdown in glioblastoma cells." (PMID 36077559, 2022). "The colony formation assays indicated that knockdown of TRAF4 suppressed the colony formation ability of glioblastoma cells." (PMID 36077559, 2022). "Knockdown of TRAF4 inhibits the growth, proliferation, migration, and invasion of glioblastoma cells." (PMID 36077559, 2022). "In the in vitro tumor formation assay, the tumor formation ability of glioblastoma cells following TRAF4 knockdown was significantly decreased." (PMID 36077559, 2022). "Western blot results showed that the growth-related proteins (CCND1 and β-catenin) of glioblastoma cells decreased following TRAF4 knockdown, consistent with previous studies." (PMID 36077559, 2022). "The results of Western blot showed that the SETDB1 expression was also decreased following TRAF4 knockdown in glioblastoma cells." (PMID 36077559, 2022). "We performed protein turnover assays and the results suggested that TRAF4 knockdown can effectively reduce the stability of SETDB1 in glioblastoma cells treated with de novo protein synthesis inhibitor cycloheximide (CHX)." (PMID 36077559, 2022). "As the results showed, the SETDB1 expression was also increased following restoring TRAF4 expression in glioblastoma cells." (PMID 36077559, 2022). "The protein expression of TRAF4 was significantly higher in glioblastoma cell lines compared to human astroglia cell SVGP12." (PMID 36077559, 2022). "To explore the role of TRAF4 on glioblastoma growth in vivo, we subcutaneously injected glioblastoma cells in mice to perform animal experiments." (PMID 36077559, 2022). "These indicated that TRAF4 promoted glioblastoma proliferation, at least in part, by regulating SETDB1 stability and function." (PMID 36077559, 2022). "Here, we wanted to examine whether TRAF4 also mediates the activation of the AKT pathway in glioblastoma." (PMID 36077559, 2022). "Overall, our results reveal novel mechanisms by which TRAF4 is involved in regulating the AKT pathway, suggesting that TRAF4 may serve as a biomarker for glioblastoma and a new target for cancer therapy." (PMID 36077559, 2022). "Collectively, our findings reveal a novel mechanism by which TRAF4 mediates AKT pathway activation, suggesting that TRAF4 may serve as a biomarker and promising therapeutic target for glioblastoma." (PMID 36077559, 2022). "Similarly, we examined the intracellular AKT pathway, and the results of Western blot showed that overexpression of SETDB1 in TRAF4-knockdown glioblastoma restored the activation of AKT pathway." (PMID 36077559, 2022). "We restored TRAF4 expression in glioblastoma cells following TRAF4 knockdown." (PMID 36077559, 2022). "These reveal the ubiquitination role of TRAF4 in glioblastoma and may provide new insights and targets for glioblastoma diagnosis and treatment." (PMID 36077559, 2022).
glioblastoma (continued). "In glioblastoma (GBM), TRAF4 regulates caveolin 1 (CAV1) stability, and drives GBM cell stemness and temozolomide resistance by blocking ZNRF1-mediated ubiquitination and promoting USP7-mediated deubiquitination." (PMID 36765039, 2023). "Our findings clarify the reasons for the high expression of TRAF4 and the abnormal activation of the AKT pathway in glioblastoma." (PMID 36077559, 2022). "Immunoprecipitation experiments showed that both TRAF4 and SETDB1 interacted with AKT1 in glioblastoma cells." (PMID 36077559, 2022). "Collectively, these results strongly suggested that TRAF4 regulated cell proliferation and mediated activation of the AKT pathway in glioblastoma." (PMID 36077559, 2022). "Taken together, our study characterizes TRAF4 in glioblastoma and demonstrates that the E3 ubiquitin ligase TRAF4 can activate the AKT pathway by stabilizing the expression of SETDB1, ultimately promoting glioblastoma proliferation." (PMID 36077559, 2022). "We hypothesized that TRAF4 and SETDB1 are co-involved in the activation of the AKT pathway in glioblastoma based on previous results." (PMID 36077559, 2022). "Firstly, we validated the interaction of TRAF4 and SETDB1 with AKT1 in glioblastoma cells." (PMID 36077559, 2022). "So far, only few studies have explored the role of TRAF4 in glioblastoma, but the rather important ubiquitination regulation of TRAF4 has not been investigated." (PMID 36077559, 2022). "Detailed examination indicated that the highest expressions of TRAF1, TRAF2, TRAF3, TRAF5, and TRAF7 were in Cholangiocarcinoma (CHOL), while TRAF4 was most expressed in Uterine Corpus Endometrial Carcinoma (UCEC) and TRAF6 in Glioblastoma multiforme (GBM)." (PMID 38825674, 2024).
cervical cancer (7 papers, 2020 to 2024). A primary or metastatic malignant neoplasm involving the cervix. "It has been shown that MIR210HG promotes proliferation, migration, invasion, and epithelial-mesenchymal transition of cervical cancer cells by regulating the miR-503-5p/TRAF4 axis, resulting in tumor growth." (PMID 38706901, 2024). "For example, the upregulation of MIR210HG could promote cervical cancer progression by regulating miR-503-5p/TRAF4 axis." (PMID 35574307, 2022). "There were no significant changes in the expression of the miRNAs miR-608, miR-503-5p, and miR-337-3p or the mRNAs FXO6, TRAF4, and HMGA2, related to hepatoblastoma, cervical cancer, and endometrial cancer." (PMID 38474063, 2024). "In cervical cancer, MIR210HG might act as a competing endogenous RNA (ceRNA) of miR-503-5p to relieve the suppressive effect of miR-503-5p on TRAF4 expression, resulting in increased cell proliferation and invasive capacity." (PMID 33392077, 2020).
osteosarcoma (7 papers, 2019 to 2025). A usually aggressive malignant bone-forming mesenchymal neoplasm, predominantly affecting adolescents and young adults. "Overexpression of TRAF4 has been implicated in the regulation of tumor formation in osteosarcoma, a type of bone cancer that is common in certain dog breeds, including Mastiffs." (PMID 40971676, 2025). "TRAF4 protein levels are significantly higher in osteosarcoma tissues than in normal bone tissue, and elevated TRAF4 causes tumor cell proliferation, promotes cancer cell colony formation, enhances osteosarcoma cell proliferation and invasion, and increases Ki67 expression through the AKT pathway." (PMID 35242717, 2022). "Reduction of TRAF4 expression promoted inhibitory effects on the proliferative ability of osteosarcoma cell culture; CDK5, member of the family of cyclin-dependent kinases, plays a role in DNA damage response and cell cycle checkpoint activation." (PMID 30908498, 2019). "TRAF4 activates the AKT signaling cascade to enhance osteosarcoma cell proliferation and invasion." (PMID 36625999, 2023). "Thus, targeting SETDB1 in osteosarcoma would represent a potential therapeutic strategy, as it would downregulate both SKP2 and TRAF4 (and their ability to activate AKT)." (PMID 38534381, 2024).
prostate carcinoma (7 papers, 2019 to 2025). A carcinoma that arises from epithelial cells of the prostate gland. "Additionally, TRAF4 overexpression has been implicated in prostate cancer, where it mediates K27-linked ubiquitination of the AR C-terminus, elevates intracellular cAMP levels, enhances E2F transcription factor activity, and promotes cell proliferation." (PMID 40990020, 2025). "Elevated TRAF4 levels correlated significantly with increased NGF-stimulated invasion-related gene expression in prostate cancer patients, suggesting that this signaling axis is activated substantially during tumorigenesis." (PMID 35242717, 2022). "Through the TGF-β signaling pathway, TRAF4 promotes cancer cell migration and invasion in breast and prostate cancers." (PMID 35242717, 2022). "Additionally, another study indicated that TRAF4 plays a significant role in desmoplasia-resistant prostate cancer, a condition that presents a major clinical challenge, where the androgen receptor (AR) remains a key oncogenic factor." (PMID 40771930, 2025). "In prostate cancer, TRAF4 promotes cancer cell proliferation through the RTK signaling pathway." (PMID 35242717, 2022). "TRAF4 is a target gene of miR-519d-3p, down-regulated in prostate cancer cells." (PMID 35242717, 2022). "In addition, K27- and K29-linked ubiquitination of TrkA, a neurotrophin receptor tyrosine kinase, by TRAF4 increases TrkA kinase activity to enhance prostate cancer metastasis." (PMID 32357935, 2020). "miR-519d-3p overexpression significantly reduced the expression of TRAF4 and its downstream TGF-β signaling pathway proteins in prostate cancer cells, thereby inhibiting the proliferation of prostate cancer cells." (PMID 35242717, 2022).
colon cancer (6 papers, 2016 to 2025). "In a liver metastasis model of colon cancer, the results showed that nuclear TRAF4 overexpression in TRAF4‐KO HCT116 cells resulted in the formation of more and larger metastatic nodules in livers compared with the TRAF4‐KO or cytoplasmic TRAF4 group." (PMID 39716976, 2025). "Ubiquitination of LAMTOR1 by TRAF4 promoted its binding to Rag GTPases and enhanced mTORC1 activation, K151R knock‐in or TRAF4 knock‐out blocks amino acid‐induced mTORC1 activation and accelerates the development of inflammation‐induced colon cancer." (PMID 38229144, 2024). "We found that TRAF4 was upregulated in colon cancer and that high expression levels of TRAF4 were positively correlated with poor prognosis." (PMID 38229144, 2024). "Through TCGA data analysis, we found that TRAF4 is highly expressed in human CRC and that high expression of TRAF4 is positively correlated with increased mTORC1 activity in colon cancer samples." (PMID 38229144, 2024). "Surprisingly, using a mouse model, we found that TRAF4 inhibits inflammation‐induced colon cancer progression, possibly via the ubiquitination of LAMTOR1." (PMID 38229144, 2024). "Our data showed that the increased TRAF4 protein expression levels were positively correlated with elevated mTORC1 activity (monitored by the level of p‐S6K) in colon cancer tissues." (PMID 38229144, 2024). "Previous studies have shown that LEP up-regulates miR-4443, thereby suppressing NCOA1 and TRAF4, and decreasing the invasiveness of human colon cancer cells." (PMID 37282602, 2023). "TRAF4 promoted the growth and invasion of colon cancer cells by enhancing the Wnt/β catenin pathway to promote colon cancer cell growth and invasion." (PMID 35242717, 2022). "To examine whether TRAF4 expression was correlated with mTORC1 activity, we performed tissue microarray analysis of TRAF4 expression and mTORC1 activation in colon cancer samples." (PMID 38229144, 2024). "TRAF4 was overexpressed in colon cancer tissues and cells, and TRAF4 knockdown inhibited cell proliferation, invasion, and tumorigenesis in vitro and in vivo and induced apoptosis in colon cancer cells." (PMID 35242717, 2022). "In conclusion, we propose a mechanistic model in which Ragulator‐mediated mTORC1 activation is regulated by the TRAF4‐catalyzed ubiquitination of LAMTOR1 at K151, which regulates the development of inflammation‐induced colon cancer." (PMID 38229144, 2024). "Although we could not determine the types of CRC, our data suggest that TRAF4 promotes colon cancer in humans via mTORC1 activation." (PMID 38229144, 2024).
colorectal cancer (6 papers, 2022 to 2025). A primary or metastatic malignant neoplasm that affects the colon or rectum. "Through the β-catenin signaling pathway, TRAF4 increases resistance to chemotherapeutic agents in breast and colorectal cancers." (PMID 35242717, 2022). "TRAF4 catalyzes ubiquitination of CHK1 in several colorectal cancer (CRC) cell lines." (PMID 35242717, 2022). "Additionally, the TRAF4-mediated ubiquitination of LAMTOR1 drives mTORC1 activation in colorectal cancer, suggesting that TRAF4 inhibitors could suppress oncogenic signaling." (PMID 40427667, 2025). "TRAF4 facilitates the ubiquitination of JNK1/2 and activates the JNK/c-Jun pathway to drive radioresistance in colorectal cancer." (PMID 38164179, 2024). "TRAF4 was found to catalyze the ubiquitination of the DNA-damage checkpoint kinase 1 (CHK1) at the K132 site to induce its phosphorylation and activation, resulting in chemotherapy resistance in colorectal cancer." (PMID 36535926, 2022). "Moreover, TRAF4 is the first member of the TRAF protein family to be amplified and overexpressed in multiple human malignancies, including breast, lung, prostate and colorectal cancer, and OSCC." (PMID 36535926, 2022).